TNF (tumor necrosis factor)
Diseases named in the same sentence as TNF in open-access papers (continued):
Sharing a sentence is not in itself a finding about the gene and the disease.
atherosclerosis (continued). "Subsequent pathway classification showed that the TNF signaling pathway was the most significant, followed by the NOD-like receptor signaling pathway, while the Lipid and atherosclerosis pathways were also prominently present in the classification." (PMID 40725488, 2025). "Th1 cells release tumor necrosis factor (TNF-α) and interferon-γ (IFN-γ), which play a role in promoting atherosclerosis." (PMID 41462995, 2025). "Curcumin has been shown to inhibit the expression of pro-inflammatory mediators, such as C-reactive protein (CRP), TNF-α, IL-1β, and intercellular adhesion molecule-1 (ICAM-1), which play crucial roles in the development and progression of atherosclerosis." (PMID 39941147, 2025). "Inflammation is a key driver of atherosclerosis, with CRP, IL-6, and TNF-α serving as markers of disease activity." (PMID 40217801, 2025). "Crucially, the CSRDEGs were intricately associated with several key biological pathways, as identified by KEGG, including lipid metabolism and atherosclerosis, regulation of apoptosis, the MAPK signaling pathway, and the TNF signaling pathway." (PMID 40520613, 2025). "For instance, in atherosclerosis, MCP-1 and TNF-α are two inflammatory mediators released during foam cell formation." (PMID 40489926, 2025). "Given the key role of inflammation in atherosclerosis, we performed immunostaining to assess the expression of inflammatory markers IL-1β, MCP-1, NF-κB, TNF-α, IFN-γ." (PMID 40953531, 2025). "The KEGG results implied that the pathways with relatively high counts were intimately connected with atherosclerosis, tumor, virus infection, HIF-1 signaling pathway, MAPK signaling pathway, TNF signaling pathway, and cAMP signaling pathway." (PMID 39936089, 2025). "Regarding pathways, the four with the highest correlation were identified as the HIF-1 Signaling pathway, the lipid and atherosclerosis signaling pathway, the PI3K/Akt signaling pathway, and the TNF signaling pathway." (PMID 38835897, 2024). "These pathways include Fluid shear stress and atherosclerosis, Lipid and atherosclerosis, AGE-RAGE signaling pathway in diabetic complications, IL-17 signaling pathway, and TNF signaling pathway." (PMID 38528143, 2024). "The purpose of these trials is to assess mRNA vaccines for their potential to lower pro-inflammatory cytokines such as IL-1β and TNF-α, which are known to promote plaque progression, as well as LDL-C, a major driver of atherosclerosis." (PMID 39712846, 2024). "In atherosclerosis and coronary heart disease, an HFD elevates IL-6, C-reactive protein (CRP), and TNF-α preceding endothelial dysfunction and nitric oxide depletion." (PMID 38999835, 2024). "The proinflammatory Th1 response can upregulate atherosclerosis through the secretion of IFN-γ, TNF-α, IL-1, IL-6, and IL-12." (PMID 38579073, 2024). "With the progression of atherosclerosis, inflammatory cells and macrophages that engulf oxidized LDL-C are noted to release pivotal inflammatory mediators such as tumor necrosis factor-alpha, interleukin-8, and interleukin-1." (PMID 39364366, 2024). "Our study revealed that common targets of kaempferol and OP are mainly involved in the Atherosclerosis-related signaling pathways, AGE/RAGE signaling pathway, and TNF signaling pathway." (PMID 38528143, 2024). "This study aimed to measure the associations between different inflammatory factors, namely interleukin (IL)-17A, tumor necrosis factor (TNF)-α, and high-sensitivity C-reactive protein (hs-CRP), and atherosclerosis in patients with psoriasis vulgaris." (PMID 39104857, 2024). "TNF- α also promotes the production of genes producing IL-6 and MCP-1, which contributes to the advancement of atherosclerosis." (PMID 38266537, 2024). "Specifically, mouse-derived B2 cells produce IgG that inducesinflammation; they also play a role in atherosclerosis development bysecreting TNF-α, increasing macrophage tumor necrosis factor-α (TNF-α) production, andpromoting cell death and inflammation." (PMID 39355583, 2024).
atherosclerosis (continued). "Various inflammatory stimuli such as interleukin-6 (IL-6), tumour necrosis factor-alpha (TNF-α) and intercellular adhesion molecule 1 (ICAM-1) play major roles in atherosclerosis." (PMID 39769058, 2024). "Pro-inflammatory signaling molecules, including interleukin-1β (IL-1β), tumor necrosis factor-α (TNF-α), and interleukin-6 (IL-6), are notably elevated in both IBD and atherosclerosis." (PMID 38558708, 2024). "Pro-inflammatory markers like IL-6, tumor necrosis factor-alpha (TNF-alpha), and CRP that are markedly increased in RA play a role in accelerating atherosclerosis and myocardial fibrosis development." (PMID 39712804, 2024). "EPA and DHA exert their anti-inflammatory effects by inhibiting the production of pro-inflammatory cytokines such as interleukin-1 (IL-1) and tumor necrosis factor-alpha (TNF-α), which contribute to vascular inflammation and atherosclerosis." (PMID 39796335, 2024). "In this study, through comprehensive analysis methods, four key genes—CCL3, TNF, CCR2, and CCR5—were identified, having significant impacts on the pathophysiological mechanisms of gout and atherosclerosis." (PMID 39677038, 2024). "The primarily enriched pathways included atherosclerosis-related signaling pathways, the AGE/RAGE signaling pathway, and the TNF signaling pathway." (PMID 38528143, 2024). "Nevertheless, the level of proinflammatory cytokines such as TNF-α, IL-1β, IL-6, and IFN-γ was also found to be elevated in several heart diseases including congestive heart failure, atherosclerosis, coronary artery disease and myocardial infarction." (PMID 38441007, 2024). "The association of ENST00000416361 with inflammatory cytokines (IL-6 and TNF-α) and lipid metabolism-related genes (SREBP1 and SREBP2) suggests its involvement in atherosclerosis pathogenesis through inflammation and lipid metabolism." (PMID 39273193, 2024). "Atherosclerosis (AS) is a chronic inflammatory disease where the release of pro-inflammatory cytokines (e.g. IL1β, IL6, and TNF) promotes its development." (PMID 39044161, 2024). "KEGG enrichment analysis showed that DEGs were significantly enriched in pathways related to HIF-1, TNF, IL-17 signaling, AGE-RAGE signaling pathway in diabetic complications, and Fluid shear stress and atherosclerosis." (PMID 38439898, 2024). "Previous studies have shown that high doses of crocin proportionally reduce the levels of macrophages and their inflammatory derivatives in atherosclerosis, including MCP-1, TNF-α, IL-6, MMP-2, MMP-3, and MMP-9." (PMID 38830933, 2024). "CTRP9 demonstrated significant protective effects against atherosclerosis, including enhancing plaque stability by activating AMPK, inhibiting levels of adhesion molecules in atherosclerotic plaques, and reducing MCP-1 and TNF-α secretion." (PMID 38704561, 2024). "The lipid and atherosclerosis pathway, for example, involves several inflammation-related targets such as AKT1, TNF, and IL6, underscoring chronic inflammation’s critical role in atherosclerosis progression." (PMID 39822742, 2024). "In atherosclerosis, oxidized low-density lipoprotein (ox-LDL) and pro-inflammatory cytokines such as Interleukin-6 (IL-6) and Tumor Necrosis Factor-alpha (TNF-α) activate immune cells contributing to foam cell formation and arterial wall thickening." (PMID 39877020, 2024). "Secondly, AKT1 and MMP9 are both enriched in multiple signaling pathways, such as Fluid shear stress and atherosclerosis, Lipid and atherosclerosis, AGE-RAGE signaling pathway in diabetic complications, and TNF signaling pathway." (PMID 38528143, 2024). "The KEGG pathway analysis of overlapping genes suggested relevant pathways such as lipid and atherosclerosis, PI3K-AKT, insulin signaling, advanced glycation end product (AGE)-RAGE, TNF, and mitogen-activated protein kinase (MAPK)." (PMID 39598338, 2024). "In atherosclerosis, ox-LDL and cytokines like IL-6 and TNF-α drive foam cell formation and arterial thickening." (PMID 39877020, 2024).
atherosclerosis (continued). "Inflammatory cytokines, such as tumor necrosis factor alpha (TNF-α), interleukin 1 beta (IL-1β), and interleukin 6 (IL-6), are pivotal in the inflammatory response that characterizes atherosclerosis." (PMID 38831182, 2024). "Ox-LDL receptor-1 (OLR-1/LOX-1), tumor necrosis factor alpha (TNF-α), and atherogenic interleukins (IL-1β, IL-6, etc.)play an important role in the pathogenesis of atherosclerosis." (PMID 39770544, 2024). "The DGs of DS group were mainly enriched in the TNF signaling pathway, the ECM-receptor interaction pathway, cancer pathways, the lipid and atherosclerosis pathway, and complement and coagulation cascades, among other pathways." (PMID 38789486, 2024). "Investigating whether inflammatory stimuli like TNF affect extracellular matrix gene expression and elucidating the consequences of such changes for vascular integrity may provide further understanding of the molecular mechanisms driving atherosclerosis development." (PMID 39201392, 2024). "Thepro-inflammatory cytokines tumor necrosis factor alpha (TNF-α),interleukin 1 (IL-1), interferon-γ, are also activated in thepathogenesis of atherosclerosis." (PMID 39077646, 2024). "Our analysis revealed significant associations with several key signaling pathways, notably lipid and atherosclerosis, PI3K-Akt, MAPK, AGE-RAGE, and TNF signaling pathways." (PMID 38666923, 2024). "Preclinical studies in murine models have shown that IL-6 promotes atherosclerosis and possibly plaque vulnerability and that injection of IL-6 results in increased CRP, TNF-α, and fibrinogen levels." (PMID 37629526, 2023). "As TNF-α, NF-κB, NLRP3, and IL-1β are crucial genes in the formation of ASC plaques to formulate atherosclerosis, we evaluated their expression in the aorta by Q-PCR." (PMID 37836470, 2023). "Furthermore, TNF, known as one of the main proinflammatory cytokines regulating the inflammatory response in autoimmune arthritis, is associated with the severity of subclinical atherosclerosis in RA, regardless of traditional cardiovascular risk factors." (PMID 36763689, 2023). "Its main pathway involves AGE-RAGE signaling pathway in diabetic complications, pathways in cancer, lipid and atherosclerosis, HIF-1 signaling pathway, TNF signaling pathway, IL-17 signaling pathway." (PMID 37800753, 2023). "CD14++CD16− produces low levels of tumor necrosis factor alpha (TNF-α) and high amount of IL-10, whereas CD14+CD16++ secretes high levels of pro-inflammatory cytokines promoting atherosclerosis." (PMID 37600028, 2023). "Few recent studies indicated the signaling pathway of TUG1 by increasing TNF via the activation of the NF-KB pathway by regulating miR-26a/HMGB1 and development of atherosclerosis through modulating miR-21/phosphatase." (PMID 37736902, 2023). "Further, the concept that OSM mediates plaque vulnerability is supported by the fact that OSM and TNF-α colocalize in atherosclerotic plaques and TNF- α plays a critical role in early as well as late stages of atherosclerosis." (PMID 36856919, 2023). "Tumor necrosis factor (TNF) binding to endothelial TNF receptor-I (TNFR-I) facilitates monocyte recruitment and chronic inflammation, leading to the development of atherosclerosis." (PMID 37834170, 2023). "Due to the inhibition of RhoA/ROCK/NF-κB signaling in human endothelial cells ECV-304, SFN attenuated TNF-α-induced ICAM-1 expression, as well as IKK phosphorylation, suggesting a beneficial role in the atherosclerosis-related inflammation." (PMID 36823573, 2023). "Our results showed that the topmost enriched pathways in endothelial cells during C. albicans infection were TNF (tumor necrosis factor), AGE-RAGE signaling, NF-κB signaling, MAPK signaling, lipid, and atherosclerosis." (PMID 37511508, 2023).
atherosclerosis (continued). "TIPE2 can accelerate the differentiation of M2 macrophages by activating the PI3K signaling pathway, significantly reduce the expression of TNF-α, IL-6, and MCP-1, and play a protective role in atherosclerosis." (PMID 37069964, 2023). "Up-regulated DEGs included known atherosclerosis genes such as the liver X receptor gene NR1H2, and NEXN, TRAF1, TLR7 and LGALS3BP, implicating tumor necrosis factor and toll-like receptor signaling and glycan-binding protein pathways." (PMID 37205656, 2023). "According to a study, Tanshinone IIA downregulated the NF-κB activity, and reduced the expression of TNF-α and MCP-1, to stabilize vulnerable atherosclerosis plaque in ApoE−/− mice." (PMID 36823573, 2023). "Turmeric improves serum SOD and CAT activity; inhibits the production of inflammatory molecules, such as TNF-α, IL-6, COX-2, and 5-LOX; prevents endothelial dysfunction; and suppresses cholesterol accumulation in macrophage foam cells and atherosclerosis." (PMID 37241765, 2023). "Therefore, the modulation of Shank3 expression may be associated with inflammation-related disorders, such as atherosclerosis, rather than only affecting the brain, through the suppression of TNF-α-mediated inflammation cascades." (PMID 37947623, 2023). "Overall, our enrichment analysis showed that the topmost enriched pathways in endothelial cells were TNF (tumor necrosis factor) signaling, AGE-RAGE signaling, NF-κB signaling, MAPK signaling, lipid, and atherosclerosis." (PMID 37511508, 2023). "Mercury exposure activates p38 MAPK and increases the expression of TNF-α and interferon gamma (IFN-γ), which promote atherosclerosis." (PMID 37396849, 2023). "Therefore, CSJD may regulate targets such as PIK3CA, AKT1, TNF, IL-6, and others through the lipid and atherosclerosis pathway, block the key pathways and molecules of lipid metabolism, and thus achieve the effect of inhibiting dengue virus replication and improving clinical symptoms of patients." (PMID 38206728, 2023). "The potentially suppressed pathways in Hariana included TNF signaling pathway, HIF-1 signaling pathway, IL-17 signaling pathway, cytokine-cytokine receptor interaction and fluid shear stress and atherosclerosis." (PMID 37127630, 2023). "We found that the combined inhibition of TNFα, CXCL2 and CCL2 in recipients with aged fat transplants substantially reduced the degree of atherosclerosis at the carotid artery, aortic root and BCA." (PMID 36683460, 2023). "TNF-α and IL-8 in GCF showed moderate accuracy in predicting subclinical atherosclerosis, whereas IL-1β in GCF had low accuracy." (PMID 36983201, 2023). "SIN mainly affected 5 target genes, NFκB-1, TNF, interleukin 6, interleukin 1β and signal transducer and activator of transcription 3, and IL-17, AGE-RAGE signaling pathways, lipids, and atherosclerosis were all controlled to achieve therapeutic effects." (PMID 38206710, 2023). "KEGG pathway enrichment analysis showed that common pathways included tumor necrosis factor signaling pathway, NF-κB signaling pathway, NOD-like receptor signaling pathway, lipid and atherosclerosis, lipoprotein particle binding, and apoptosis." (PMID 37189834, 2023). "The crucial KEGG pathways were the TNF signaling pathway, alcoholic liver disease, NOD-like receptor signaling pathway, lipid and atherosclerosis, and biosynthesis of amino acids." (PMID 36017103, 2022). "Others have demonstrated that IL-6 and TNF-a become elevated in PAD patients after exercise treadmill testing, suggesting that inflammatory markers increase in conditions of atherosclerosis and hemodynamic stress." (PMID 36582735, 2022). "In patients with atherosclerosis, increased expression of CD160 on NK cells stimulates the production of TNF-α, which leads to NK cell apoptosis and a subsequent decrease in the number of circulating NK cells." (PMID 35464400, 2022).
atherosclerosis (continued). "ACA treatment also reduced the expression of atherosclerosis-related proteins, including CD68, α-SMA, ICAM-1, and TNFα, in the plaque area." (PMID 35563730, 2022). "NRDEGs were also enriched in KEGG pathways such as necroptosis, apoptosis, TNF signaling pathway, NOD-like receptor signaling pathway, innate immune response, cytokine stimulus-response, inflammatory response, and lipid and atherosclerosis." (PMID 36619743, 2022). "Studies have shown that inflammatory factors such as TNF-α and hs-CRP were involved in the process of atherosclerosis and interact with this process." (PMID 35186231, 2022). "Tumor necrosis factor (TNF)-α, a pro-inflammatory cytokine involved in the pathogenesis of axSpA, is also involved in the initiation and progression of atherosclerosis and in rupture of atherosclerotic plaque." (PMID 35698171, 2022). "Anti-PC-IgM boosts Tregs, lowers IL-17 and TNF-alpha in SLE and atherosclerosis, and renders dendritic cells (DCs) immature." (PMID 35282557, 2022). "TMAO furtherpromotes atherosclerosis by activating the CD36-dependent MAPK/Janus kinases(JAKs) pathway and triggering the expression of VCAM-1, TNF-α andIL-1β via the NF-κB pathway." (PMID 39077721, 2022). "TNF, a proinflammatory cytokine produced by macrophages, was also a central regulator of the inflammatory response and may be involved in the pathogenesis of atherosclerosis through its effects on endothelial cell function, lipid metabolism, and enhanced vascular inflammatory response." (PMID 35223093, 2022). "Then they stimulated the model with pro-inflammatory cytokines (such as TNF-α and IL1-β) and oxidized LDL for studying endothelial inflammation in early atherosclerosis." (PMID 35208450, 2022). "APN expression can inhibit monocyte adhesion to TNF-α-treated endothelial cells by activating the AMPK signaling pathway, affecting the early stages of atherosclerosis." (PMID 36555264, 2022). "Furthermore, the KEGG pathway analysis indicated that the lipid and atherosclerosis pathways, prostate cancer pathway, apoptosis pathway, fluid shear stress and atherosclerosis pathways, and TNF signaling pathway may be correlated with the therapeutic effects of FZHY on renal fibrosis." (PMID 36569327, 2022). "Pathways identified by KEGG analysis included those involved in lipid and atherosclerosis, the PI3K-Akt signaling pathway, MAPK signaling pathway, TNF signaling pathway, cancer-related signaling pathways, and numerous immune-related signaling pathways." (PMID 36091226, 2022). "The perfused nutrient medium combined some risk factors such as low-density lipoprotein (LDL), monocytes, and tumor necrosis factor-alpha (TNF-α), and acquired LDL accumulated in the sub-endothelial space, which is an early development of atherosclerosis." (PMID 35208450, 2022). "Visceral and ectopic fat accumulation in NASH is associated with an over-secretion of FFAs and a number of adipocytokines, including TNF-a, IL-6, and PAI-1, promoting vascular inflammation and endothelial dysfunction, a marker of early atherosclerosis." (PMID 35739957, 2022). "The 5 most enriched KEGG pathways were the TNF signaling pathway, alcoholic liver disease, NOD-like receptor signaling pathway, lipid and atherosclerosis, and biosynthesis of amino acids." (PMID 36017103, 2022). "Decreases the adhesion of monocytes to TNF-α-stimulated VSMCs; down-regulates p38 MAPK, JNK and ERK, NF-κB and TNFR1 expression; inhibits vascular inflammation; and shows potential to prevent atherosclerosis." (PMID 35566359, 2022). "Many cytokines including TNF-α, IL-1β, and MCP-1 are expressed in atherosclerotic plaques, which impact foam cell formation and the progression of atherosclerosis." (PMID 36387364, 2022).